DUSP2 (dual specificity phosphatase 2)
Diseases named in the same sentence as DUSP2 in open-access papers (continued):
Sharing a sentence is not in itself a finding about the gene and the disease.
cancer (continued). "A comprehensive analysis of microRNA and DUSP2 mRNA expression data across 32 cancer types revealed significant inverse correlations between oncogenic microRNA clusters (miR-17-92, miR-106a-363, and miR-106b-25 cluster) and DUSP2 expression in various cancer types." (PMID 40537745, 2025). "However, it is difficult to evaluate the possible involvement of DUSP2 in tumorigenesis and treatment response due to the incomplete understanding of the molecular mechanisms controlling its expression in cancer." (PMID 40537745, 2025). "However, the upregulation of DUSP2 has been shown to have both pro- and anti-tumorigenic effects in different cancer types." (PMID 37834191, 2023). "Thus far DUSP2−/− mice have not been crossed into any of the commonly used murine cancer models and reports of the involvement of DUSP2 in cancer are relatively scant." (PMID 30401534, 2019). "DUSP1 and DUSP2 were down-regulated in several types of cancers." (PMID 29422643, 2018). "Previously it has been reported that DUSP2 expression is downregulated in many human cancers." (PMID 26833217, 2016). "Thus, we observed a methylation dependent silencing of DUSP2 in cancer cell lines, which was reversed by inhibiting DNA methylation." (PMID 26833217, 2016). "Downregulation of the dual specificity phosphatase 2 (DUSP2) has been reported in cancer." (PMID 26833217, 2016). "Deletion of the DUSP2 locus at 2q11.2 is rather infrequent in cancer." (PMID 26833217, 2016). "DUSP2 downregulation was previously observed in different types of cancer." (PMID 25596742, 2015). "The DUSP2 connection in our model is based on data from fibroblast and cancer cell lines (see Sec." (PMID 23060802, 2012). "The role of DUSP2 in cancer has been examined in only a few studies, and data are controversial." (PMID 22118688, 2011). "Thus, the direct regulation of DUSP2 by miR-106b-5p and miR-93-5p might provide another component in the regulatory network of MAPKs in respective cancer types and requires to be further investigated." (PMID 40537745, 2025). "Seventeen microRNAs showed high expression levels in 90% of all tumour samples (CPM > 1) and most (16 microRNAs) were significantly negatively correlated to DUSP2 mRNA expression in respective cancer types which could indicate a microRNA-induced mRNA degradation (p < 0.05)." (PMID 40537745, 2025). "Interestingly, low expression of DUSP2 and high expression of HIF-1α were associated with poor prognosis in ER-negative BC patients, further supporting the relevance of a HIF1α/DUSP2/ERK axis in cancer." (PMID 40943262, 2025). "In addition, it has also been suggested that DUSP2 plays a role in apoptosis and cancer." (PMID 36160033, 2022). "In addition, it has also been proposed that DUSP2 plays a role in apoptosis and cancer." (PMID 31293510, 2019). "In addition, we also found that DUSP1 and DUSP2 were down-regulated in several types of cancers." (PMID 29422643, 2018). "Experiments conducted on cancer cell lines (HeLa, HCT116, and Hep3B) indicated that HIF-1α inhibits transcription and translation of DUSP2, leading to sustained ERK1/2 phosphorylation and increased chemoresistance." (PMID 40943262, 2025). "At present, no study has yet to disclose the relationship between MAGI2-AS3 and DUSP2, or FOXA1 and MAGI2-AS3 in cancer." (PMID 36998469, 2023). "On one hand, hypoxia‐mediated downregulation of dual specificity phosphatase 2 (DUSP2) upregulates COX‐2, leading to increased cancer stemness." (PMID 36226253, 2022). "Thus, DUSP-2 might be the link that connects hypoxia and Golgi fragmentation in cancer." (PMID 35563790, 2022). "Therefore, induction of DUSP1 and DUSP2 might be a therapeutic strategy for treating cancer." (PMID 29422643, 2018). "In cancer cells lines (H322, ZR75-1) and HEK293 cells, that exhibit a methylated promoter, expression of DUSP2 was reduced compared to HeLa and H358 cells, which harbor unmethylated promoter regions." (PMID 26833217, 2016).
cancer (continued). "Although dysregulated microRNAs have been associated with MAPK pathway activation and carcinogenesis, little is known about the role of microRNA-mediated regulation of negative MAPK pathway regulators such as DUSP2 in cancer context." (PMID 40537745, 2025). "DUSP2 belongs to the nuclear DUSP family, specifically type I, and it inhibits the activation of MAPK while having a crucial function in immune processes, inflammatory responses, and the advancement of cancer." (PMID 38714855, 2024). "We then performed a simple pan-cancer analysis of DUSP2 expression, which showed that DUSP2 expression was not tissue-specific and was downregulated in some cancer tissues when compared with normal tissues, including PCa." (PMID 36998469, 2023). "DUSP2 regulates MAPK activity and plays an essential role in cell proliferation and cancer." (PMID 32306542, 2020). "In addition, our bioinformatics analysis revealed that miR-20a regulated several cancer-related genes, particularly tumor suppressor genes, such as PTEN, BCL2L11, FBXO31, and DUSP2." (PMID 33125430, 2020). "The expression of CRTAC1, DUSP2, ATOH8, and HIST2H2AC showed a significantly negative correlation with the activity of most hallmark-cancer pathways." (PMID 33604353, 2020). "DUSP-2 has a negative function in cancer malignancy and COX-2 is closely related to cancer stemness, tumor growth and drug resistance." (PMID 31709180, 2019). "Previously it has been reported that DUSP2 expression is markedly reduced or completely absent in many human cancers." (PMID 26833217, 2016). "Previously it has been shown that expression of the MAPK-specific phosphatase DUSP2 is markedly reduced or completely absent in many human cancers and that its level of expression inversely correlates with cancer malignancy." (PMID 26833217, 2016). "The role of DUSP2 and DUSP8 genes coding phosphatases regulating MAPK signaling pathway confirmed the contribution of these target genes to the development and progression of many cancers." (PMID 27152840, 2016). "Lin and colleagues were the first to provide evidence for an antitumour role of DUSP2, demonstrating that its expression is markedly diminished or absent in many human cancers, with expression levels inversely correlating with both HIF-1α expression and tumour malignancy." (PMID 40943262, 2025). "Additionally, 11 of the 17 microRNAs highly expressed in certain cancer types (CPM > 1) also exhibited significant negative correlations with DUSP2 mRNA levels (p < 0.05)." (PMID 40537745, 2025). "The aim of the present study was to investigate whether microRNA-mediated regulation of DUSP2 could contribute to an impairment of negative feedback regulation in cancer." (PMID 40537745, 2025). "For example, dual specificity phosphatase 2 (DUSP2), a mitogen-activated protein kinase (MAPK) phosphatase that regulates phospho-signaling downstream of the TCR, is highly expressed in tumor-infiltrating CTLs and negatively correlates with cancer patient survival." (PMID 37239368, 2023). "Moreover, DUSP2, p-ERK1/2 and EMT-related markers were examined in human PDAC tissues, which revealed that the miR-361-3p level in cancer tissues correlated negatively with the expression of DUSP2 and E-cadherin and positively with p-ERK, Vimentin and N-cadherin, respectively." (PMID 30042387, 2018). "The result is particularly interesting in the context of (a) cancer, as many cancers show increased expression of DUSP1 and reduced expression of DUSP2, and (b) tumor related conditions such as hypoxia, where low oxygen levels upregulate DUSP1 and downregulate DUSP2." (PMID 23060802, 2012). "The results of this study indicate that microRNA-mediated regulation of DUSP2 in hematologic and solid cancers appears to be a plausible mechanism that contributes to the dysregulation of MAP kinase signaling pathways in cancer by impairing negative feedback regulation." (PMID 40537745, 2025).
cancer (continued). "However, it must be taken into account that the analysed number of available microRNA and DUSP2 expression as well as MAPK phosphorylation data varied markedly between the TCGA cancer types and normal control data were not available for all cancer types." (PMID 40537745, 2025).
tumor (26 papers, 2011 to 2025). "Several known tumor suppressor genes were selected and validated via qRT‐PCR, with Dual‐Specificity Phosphatase‐2 (DUSP2) being one of the most distinctly upregulated genes." (PMID 39287090, 2024). "These altogether suggested that DUSP2 was important for immune cell infiltration in tumor pathology." (PMID 36998469, 2023). "In this study, GSEA for DUSP2 was performed and we found that the tumor immune-related signaling pathways enriched in low expression of DUSP2." (PMID 36998469, 2023). "TRIM21 inhibits tumor cell apoptosis by promoting ubiquitin-dependent degradation of dual-specificity phosphatase 2 (DUSP2)." (PMID 38174069, 2023). "We assessed this ceRNA axis’ value in the diagnosis of PCa and evaluated the potential relationship between DUSP2 and tumor-infiltrated immune cell levels." (PMID 36998469, 2023). "The results showed that the SCPEP1 gene was highly expressed in BRCA, KIRC and THCA tumour types, and the DUSP2 gene was more expressed in KICH, LIHC and BRCA." (PMID 37091857, 2023). "Our research confirms that DUSP2 plays a tumor suppressive role in GC and that DUSP2 binds to ERK1/2, thereby promoting its dephosphorylation and inhibiting the MAPK/ERK pathway, resulting in EMT and reduced GC invasion and even peritoneal metastasis." (PMID 35295342, 2022). "DUSP2 participates in the development of tumor through multiple signaling pathways and negatively regulates the activity of extracellular regulatory protein kinase (ERK) and p38 in vitro." (PMID 35295342, 2022). "Additionally, our observed predominant expression of DUSP2 in the tumor core is consistent with previous research findings that decreased DUSP2 expression levels are closely related to tumor growth." (PMID 41275376, 2025). "CCK-8, EdU, wound healing, and Transwell invasion assays indicated that overexpressing DUSP2 significantly inhibited the proliferation, migration, and invasion of BLCA cells, suggesting that DUSP2 may play a tumor-suppressive role in BLCA." (PMID 38507521, 2024). "Therefore, how DUSP2 participates in the tumor microenvironment and influence tumor-infiltrating immune cells in PCa caught our interest." (PMID 36998469, 2023). "Therefore, little is known about the potential mechanisms of DUSP2 in tumor progression, especially metastasis." (PMID 36217165, 2022). "Thus it will be interesting to further analyzed primary tumor tissues regarding an aberrant DUSP2 promoter hypermethylation." (PMID 26833217, 2016). "Thus in MCC a significant tumor-specific hypermethylation of DUSP2 was detected (p = 0.05, two tailed Fisher exact test)." (PMID 26833217, 2016). "At the single-cell level, the expression of DUSP2 and SLCO1B3 was significantly different between tumor tissue and normal tissue." (PMID 38507521, 2024). "In some solid tumors, the expression of DUSP2 is downregulated, and it functions as a key downstream regulator of HIF-1-mediated tumor progression and chemoresistance." (PMID 36998469, 2023). "We next performed immunohistochemistry of 164 GC tumor samples and found that SKA3 and DUSP2 were mainly expressed in the cytoplasm and nucleus." (PMID 35295342, 2022). "As shown in the volcano plot, SU decreased GZMB expression and upregulated genes related to inflammatory activation (FOS, JUN, NFKBIA, DUSP2, JAK1, PIM1), tumor immunity (CD47, PCBP2, EIF5A, PDIA3, EGR1), and DNA damage (H2AFX, DDIT3, GADD45B)." (PMID 34824394, 2021). "Among the genes upregulated in the atypical tumor compared to the nevus were: SOX10, the receptor tyrosine kinases ROS1 and NTRK3, PLA2G2A, and HOXA11, while DUSP2, PDGFD, and ELN were downregulated." (PMID 35052351, 2021).
tumor (continued). "Current studies indicate that DUSP2, DUSP4 and DUSP16 are involved in the co-adjustment between ERK1/2 and JNK, with these reports focusing on tumor cells and immune response." (PMID 25019380, 2014). "DUSP2 is a member of the nuclear type I DUSP family that may activate MAPKs, thereby preventing tumor progression." (PMID 38507521, 2024).
infection (5 papers, 2013 to 2025). The state of being infected such as from the introduction of a foreign agent such as serum, vaccine, antigenic substance or organism. "After 24 h of infection with A.hydrophila, except for the similar transcription level of Dusp2, the transcription levels of the remaining seven Dusp genes (1, 3-7, and 10) were significantly higher than the control group." (PMID 39606227, 2024). "In addition, these infection-induced T cells displayed typical memory markers, including Cd7, and a resting cell signature, reflected by Jun, Fosb, Dusp1, and Dusp2 expression." (PMID 40240341, 2025). "Consistent with a previous report, genes in the DUSP family (DUSP1, DUSP2, DUSP5 and DUSP6), which regulate MAPK signaling, were down-regulated at four time points post-infection." (PMID 23527143, 2013). "Relative to cells that had never been exposed to bacteria, challenge of macrophages with L. pneumophila resulted in high levels of I1α, Il1β, Tnfα and Dusp2 transcripts in both infected (GFP+) and neighboring uninfected (GFP−) populations by 4 hrs post infection." (PMID 25058342, 2014). "Interestingly, in this present study, whereas PCPEC displayed a strong inflammatory response to infection, genes attributed to hypoxia were found to play a more prominent role during infection in HIBCPP cells (including ZFP36L1, MXI1, KLHL24, PNRC1, CDKN1C, and DUSP2)." (PMID 33763387, 2021).
DUSP2 also shares sentences with these, for which no sentence is quoted: acute kidney injury (2 papers); melanoma (2); acute myeloid leukemia (1); allergic disease (1); bacterial infections (1); brain tumours (1); cardiovascular diseases (1); celiac disease (1); clear renal cell carcinoma (1); Glucose intolerance (1); herpes simplex infection (1); Insulin resistance (1); keratoconus (1); kidney cancer (1); leukemia (1); lung diseases (1); lupus nephritis (1); malaria (1); mesothelioma (1); metabolic disease (1); myocardial infarction (1); nevus (1); osteoporosis (1); pheochromocytoma (1); sarcoma (1); small cell lung carcinoma (1); squamous cell carcinoma (1); testicular germ cell tumours (1); uveal melanoma (1); viral infection (1).